PAGE3 (PAGE family member 3)
Synonyms: PAGE-3; GAGED1; CT16.6
Tractability: No criterion of Open Targets' tractability assessment is met for any kind of drug.
Gene: Protein-coding gene on chromosome X (55,258,415 to 55,264,916, reverse strand). Ensembl gene ENSG00000204279.
Subcellular location (Human Protein Atlas): Nuclear speckles; Nucleoplasm
Gene Ontology:
Molecular function: protein binding
Homologues: Orthologues: chimpanzee PAGE3 (97% identical), macaque PAGE3 (92% identical). Paralogues in human: XAGE5 (47% identical), XAGE3 (44% identical), PAGE2B (42% identical), PAGE5 (42% identical), PAGE1 (39% identical), PAGE2 (39% identical), PAGE4 (39% identical), XAGE2 (39% identical), GAGE10 (35% identical), GAGE1 (33% identical), GAGE2A (33% identical), GAGE12C (32% identical), and 10 more.
Diseases named in the same sentence as PAGE3 in open-access papers:
PAGE3 is named in the same sentence as 3 diseases in open-access papers, as found by Europe PMC text mining. Sharing a sentence is not in itself a finding about the gene and the disease. The quoted sentences say what the papers report.
cancer (1 paper, 2021). A tumor composed of atypical neoplastic, often pleomorphic cells that invade other tissues. "Genes whose upregulation is associated with some cancers (TMEM140, ANXA10, ZNF69, CA9, LOXL2, PAGE3, ELFN1) were also on this list, as was a putative tumor suppressor (DEC1)." (PMID 33601339, 2021).
PAGE3 also shares sentences with these, for which no sentence is quoted: infection (2 papers); tumor (1).